EME2 (essential meiotic structure-specific endonuclease subunit 2)
Description:
Non-catalytic subunit of the structure-specific, heterodimeric DNA endonuclease MUS81-EME2 which is involved in the maintenance of genome stability. In the complex, EME2 is required for DNA cleavage, participating in DNA recognition and bending. MUS81-EME2 cleaves 3'-flaps and nicked Holliday junctions, and exhibit limited endonuclease activity with 5' flaps and nicked double-stranded DNAs. MUS81-EME2 which is active during the replication of DNA is more specifically involved in replication fork processing. Replication forks frequently encounter obstacles to their passage, including DNA base lesions, DNA interstrand cross-links, difficult-to-replicate sequences, transcription bubbles, or tightly bound proteins. One mechanism for the restart of a stalled replication fork involves nucleolytic cleavage mediated by the MUS81-EME2 endonuclease. By acting upon the stalled fork, MUS81-EME2 generates a DNA double-strand break (DSB) that can be repaired by homologous recombination, leading to the restoration of an active fork. MUS81-EME2 could also function in telomere maintenance.
Synonyms: FLJ00151; SLX2B; gs125
Tractability: PROTAC: ubiquitination databases record sites on it.
Gene: Protein-coding gene on chromosome 16 (1,772,810 to 1,781,708, forward strand). Ensembl gene ENSG00000197774.
Subcellular location: Nucleus
Pathways (Reactome):
DNA Repair: Fanconi Anemia Pathway; Resolution of D-loop Structures through Holliday Junction Intermediates
Gene Ontology:
Molecular function: DNA endonuclease activity; enzyme-substrate adaptor activity; protein binding; DNA binding
Biological process: double-strand break repair; replication fork processing; resolution of mitotic recombination intermediates; telomere maintenance; mitotic intra-S DNA damage checkpoint signaling; resolution of meiotic recombination intermediates; DNA repair
Cellular component: chromosome, telomeric region; endodeoxyribonuclease complex; nuclear replication fork; Holliday junction resolvase complex; nuclear chromosome; nucleus
Genetic constraint (gnomAD): Loss-of-function variants: 58 observed, 34.69 expected, observed/expected ratio (o/e) 1.67, 90% interval 1.34 to 1.94. The synonymous counts are far from expectation, so gnomAD's model fits this gene poorly and the ratio says little. Missense variants: 695 observed, 489.91 expected, observed/expected ratio (o/e) 1.42, 90% interval 1.33 to 1.51. Synonymous variants: 334 observed, 216.8 expected, observed/expected ratio (o/e) 1.54, 90% interval 1.41 to 1.69.
Homologues: Orthologues: chimpanzee EME2 (98% identical), macaque EME2 (93% identical), pig EME2 (75% identical), mouse Eme2 (67% identical), rat Eme2 (67% identical), guinea pig EME2 (66% identical), tropical clawed frog eme2 (40% identical), Drosophila melanogaster mms4 (16% identical). Paralogues in human: EME1 (32% identical).
Diseases named in the same sentence as EME2 in open-access papers:
EME2 is named in the same sentence as 7 diseases in open-access papers, as found by Europe PMC text mining. Sharing a sentence is not in itself a finding about the gene and the disease. The quoted sentences say what the papers report.
B-cell lymphoma (2 papers, 2020 to 2024). "When compared with control spleen and other B-cell lymphoma subtypes, significantly higher expression was noticed in SMZL samples when stained for EME2 and USP24." (PMID 32457837, 2020).
Fanconi anemia (2 papers, 2022 to 2023). Fanconi anemia (FA) is a hereditary DNA repair disorder characterized by progressive pancytopenia with bone marrow failure, variable congenital malformations and predisposition to develop hematological or solid tumors. "Another two genes (EME2 and FAAP100) were significantly enriched in the Fanconi anemia pathway." (PMID 37372448, 2023).
gastric cancer (2 papers, 2022 to 2023). A primary or metastatic malignant neoplasm involving the stomach. "Furthermore, previous studies reported that EME2 is overexpressed in tumor tissue and was identified as poor prognosis-associated with prostate cancer and gastric cancer." (PMID 36816926, 2023). "Taken together, these findings revealed that the radiotherapy or chemotherapy promoted the expression of DNA repair genes (APLF, EID3, EME2, NPAS2 and POLN) of gastric cancer non-stem stem cells to trigger DNA repair, resulting in the biogenesis of GCSCs." (PMID 36153608, 2022).
breast carcinoma (1 paper, 2021). "Additionally, EME2 is differentially expressed in tamoxifen resistant breast cancer cells and associated with poor outcomes in patients who did not receive radiotherapy, but not in patients who were subjected to radiotherapy." (PMID 33662042, 2021).
cancer (3 papers, 2015 to 2023). A tumor composed of atypical neoplastic, often pleomorphic cells that invade other tissues. "Notably, we observed several novel associations between specific cancer types and genes, including RAD51C in AML, ATM in PRAD, PALB2 and EME2 in STAD." (PMID 26689913, 2015). "Given all this, these four DDR genes (EME2, MSH4, MLH3, and SPO11) have been proved to take part in the pathogenesis, progression, and prognosis of cancers." (PMID 36816926, 2023). "EME2 in conjunction with MUS81 initiate replication fork restart, indicating its increased expression could be exploited by cancer cells for enhanced DNA replication." (PMID 32457837, 2020).
EME2 also shares sentences with these, for which no sentence is quoted: prostate carcinoma (2 papers); tumor (2).